LOX (lysyl oxidase)
Diseases named in the same sentence as LOX in open-access papers (continued):
Sharing a sentence is not in itself a finding about the gene and the disease.
triple-negative breast carcinoma (14 papers, 2015 to 2025). An invasive breast carcinoma which is negative for expression of estrogen receptor (ER), progesterone receptor (PR), and human epidermal growth factor receptor 2 (HER2). "Chemoresistance is a trait of triple-negative breast cancer, but inhibiting LOX by miR-142-3p reduces collagen cross-linking and fibronectin assembly, increases drug penetration and causes the induction of apoptosis and re-sensitisation to chemotherapy." (PMID 35008515, 2021). "In a phase II study, lysyl oxidase activity, involved in forming a premetastatic niche in triple-negative breast cancer, was successfully targeted with copper-scavenging tetrathiomolybdate." (PMID 33379400, 2020). "Analysis of 56 triple-negative breast cancer (TNBC) versus 112 ER-positive breast cancer samples revealed higher LOX mRNA transcript levels in TNBC than in ER-positive breast cancer." (PMID 26265048, 2015). "miR-142-3p may be developed and tested with other LOX inhibitors to overcome chemoresistance in triple-negative breast cancer." (PMID 35008515, 2021). "The HIF-1α/miR-142-3p/LOX/ITGA5 pathway has been studied in the context of chemotherapy resistance, particularly in triple-negative breast cancers." (PMID 39857068, 2025). "Also, decreasing ECM stiffness with lysyl oxidase (LOX) inhibitors increased drug penetration and overcame chemotherapy resistance in triple negative breast cancer." (PMID 34646782, 2021). "Therefore, in this study, we chose RT-R-MDA-MB-231 cells derived from MDA-MB-231 cells, from triple negative breast cancers (TNBCs), and evaluated whether RT-R-MDA-MB-231 cells increased the levels of HIF-1α and LOX." (PMID 33126606, 2020).
liver cancer (13 papers, 2018 to 2025). An epithelial or non-epithelial malignant neoplasm that arises from the liver. "In conclusion, our results suggest that differences in LOX expression levels are associated with the overall survival of liver cancer." (PMID 40792413, 2025). "This analysis revealed that higher levels of COL1A1 and LOX, both of which are collagen‐related molecules, were associated with a worse long‐term prognosis in patients with primary liver cancer." (PMID 39703167, 2025). "The aberrant expression of lysyl oxidase (LOX) family is associated with liver cancer, but their function and prognostic value in LC remain largely unclear." (PMID 35311155, 2022). "Recent studies highlight the significant involvement of LOX in liver cancer, suggesting their potential as therapeutic targets in tumor." (PMID 40396123, 2025). "We additionally explored novel strategies such as LOX inhibition (LI) and sonoporation for overcoming stiffness-related radioresistance and enhancing the efficacy of RT in liver cancer patients." (PMID 39334323, 2024). "Sonoporation-aided LOX inhibition emerges as a promising strategy to mitigate stiffness-related resistance, offering potential improvements in liver cancer treatment outcomes." (PMID 39334323, 2024). "This study explored the effects of ECM stiffness and the inhibition of lysyl oxidase (LOX) isoenzymes on the radiation response of liver cancer in a millimeter-sized three-dimensional (3D) culture." (PMID 39334323, 2024). "Combining LOX inhibition with RT markedly increased radiation-induced DNA damage in cirrhotic liver cancer cells, enhancing their response to radiation." (PMID 39334323, 2024). "Here, we screen the lysyl-oxidase (LOX) family to clarify its contribution to chemotherapy resistance in liver cancer." (PMID 37253718, 2023). "A number of LOX-targeting drugs which have recently been reported to feature anti-cancer efficacy are likely to serve as candidates in the treatment of liver cancer." (PMID 33371259, 2020). "Furthermore, LOX inhibition can be combined with sonoporation to overcome stiffness-related radioresistance, potentially leading to better treatment outcomes for patients with liver cancer." (PMID 39334323, 2024). "Thus, in addition to synthetic compounds, LOX-inhibiting phytochemicals may be potential candidates for the treatment of liver cancer." (PMID 33371259, 2020). "Moreover, the lysyl-oxidase (LOX) family protein LOXL3 attenuates the ubiquitination of DHODH, in turn inducing the accumulation of DHODH proteins in liver cancer." (PMID 40715045, 2025). "LOX and LOXL2 stiffened the breast and liver cancer tissues." (PMID 29799025, 2018).
metastatic tumors (13 papers, 2011 to 2024). "Furthermore, high nuclear LOX expression in primary tumours was also shown to be significantly associated with high frequency of metastatic disease." (PMID 28947950, 2017). "Both LOX down- and up-regulation has been described in CRC as well as other cancers, initially, decreased LOX mRNA expression levels were reported in CRC patients with non-metastatic disease." (PMID 28947950, 2017). "If metastatic tumors with pN1 and/or M1 were excluded from analyses (all in group LOXa ≤ LOXc), the applied LOX expression level still provided a separation with a tendency to significance (p = 0.071)." (PMID 27336447, 2016). "Accordingly, LOX is highly expressed mainly in invasive tumors and is probably involved in the transition from localized to metastatic tumors, also in ccRCCs." (PMID 27336447, 2016). "The influence of hypoxia-induced LOX on two distinct steps in the metastatic process highlights LOX as an attractive therapeutic target for the reduction of metastatic disease." (PMID 22128892, 2011). "Lysyl oxidase (LOX) has been described as necessary for premetastatic niche formation in epithelium-derived malignancies and its expression level therefore correlates with risk of metastatic disease and overall survival." (PMID 32537166, 2020). "LOX seems to be important in a later tumor stage in the transition to metastatic tumors by stiffening the extracellular matrix, reorganization of the cytoskeleton, increasing cell motility, inducing EMT, hypoxia-induced migration and angiogenesis, as well as by setting up pre-metastatic niches." (PMID 27336447, 2016). "In keeping with those findings, combined use of an ROS scavenger, HIF inhibitor and LOX-targeted drug may be a productive and efficient way to improve cancer therapy for metastatic disease." (PMID 25174950, 2014). "Lysyl oxidase may be activated, which subsequently activates a cascade of proteins, such as Snail, involved in the repression of E-cadherin, and ultimately leading to epithelial-mesenchymal transition, as described for metastatic tumors." (PMID 23451260, 2013).
renal fibrosis (13 papers, 2018 to 2026). A final common manifestation of a wide variety of chronic kidney diseases characterized by glomerulosclerosis and tubulointerstitial fibrosis. "Serum LOX levels have been suggested to serve as non-invasive diagnostic biomarkers for renal fibrosis." (PMID 34064989, 2021). "Serum LOX has been proposed as a potential diagnostic biomarker for renal fibrosis." (PMID 40977522, 2025). "Reduction of copper levels in the Golgi apparatus by treatment with the copper chelator tetrathiomolybdate or by specific knockdown of copper transporter 1 (CTR1) decreased LOX activity and ameliorated renal fibrosis." (PMID 42100872, 2026). "Upregulation of LOX has been linked to ECM cross‐linking and the progression of renal fibrosis in ischemia–reperfusion injury (IRI) mouse kidneys." (PMID 40977522, 2025). "LOX inhibition reduces renal fibrosis by decreasing collagen deposition, presenting LOX as a therapeutic target for renal fibrosis." (PMID 39064752, 2024). "Previous studies revealed that serum lysyl oxidase increased after renal fibrosis, and the enhancement was significant in patients with moderate and severe renal fibrosis." (PMID 37266443, 2023). "Another group of ECM cross-linking enzymes whose increased activity is associated with tissue fibrosis is the lysyl oxidase (LOX) family, which has been reported in hepatic, pulmonary, and renal fibrosis." (PMID 36712680, 2022). "Thus, emerging evidence reveals that the LOX and LOXL family are involved in various diseases related to pathogenic tissue fibrosis, including idiopathic pulmonary fibrosis (IPF), renal fibrosis, cardiac fibrosis, hepatic fibrosis and systemic sclerosis." (PMID 33672186, 2021). "Similar trend was found between LOX expression and renal fibrosis (R2 = 0.8193, p = 0.003)." (PMID 32235836, 2020). "Similarly, hyperuricemia-induced LOX upregulation can increase fibronectin synthesis in tubular epithelial cells and promote renal fibrosis, and LOX knockdown via siRNA reduces this effect." (PMID 29732010, 2018). "However, the regulation of LOX activity in renal fibrosis is not well understood." (PMID 42100872, 2026). "(b) Overexpression of ATP7A caused an elevation of copper ions within the Golgi apparatus, resulting in increased LOX activity and enhanced ECM crosslinking, thereby promoting the progression of renal fibrosis." (PMID 42100872, 2026). "Further experiments have shown that inhibiting LOX activity effectively attenuates the EMT process in tubular epithelial cells, reduces the extent of renal fibrosis, and improves renal function parameters." (PMID 41180198, 2025). "Upregulated LOX can induce partial epithelial-mesenchymal transition (EMT) in renal tubular epithelial cells, thereby promoting the development of renal fibrosis in diabetes." (PMID 41180198, 2025). "Targeting LOX with its inhibitor BAPN significantly reduces IRI‐induced ECM over‐cross‐linking by inhibiting its expression and activity, thereby mitigating renal fibrosis." (PMID 40977522, 2025). "Similar to these results, previous studies also reported the overexpression of LOX and LOXL-2 in various pathological conditions characterized by fibrotic phenotypes, including IPF, renal fibrosis, cardiac fibrosis, skin aging and systemic sclerosis." (PMID 33672186, 2021).
head and neck cancer (11 papers, 2011 to 2026). A primary or metastatic malignant neoplasm affecting the head and neck. "LOX expression is associated with metastasis and poor survival in patients with breast or head and neck cancer." (PMID 37786649, 2023). "The enzyme lysyl oxidase (LOX), which initiates cross-linking in the extracellular space, is elevated in response to hypoxic microenvironments and various cytokines, and is associated with metastasis and poor survival in breast and head-and-neck cancer." (PMID 30105016, 2018). "Recently, LOX has been clinically validated as a prognostic biomarker for metastatic head and neck cancer." (PMID 28947950, 2017). "Studies in breast and head and neck cancers have shown that hypoxia-induced lysyl oxidase (LOX) is essential for tumor metastasis as LOX covalently modifies collagens to increase focal adhesion kinase activity, cell migration, and metastasis." (PMID 24216979, 2013). "The expression of the LOX gene was foundhigher in all tumour cell populations relative to adjacent and normal cells consistent with the fact that higher expression of LOX has beenassociated to hypoxia-induced metastasis in breast, head, neck cancers." (PMID 21479216, 2011). "They produce abundant fibrillar collagen and promote lysyl oxidase (LOX)‐mediated collagen crosslinking, increasing matrix stiffness and impairing drug delivery, particularly in myofibroblastic CAF subsets such as those in head and neck cancers, where NOX4/ROS‐dependent activation is involved." (PMID 41486497, 2026).
cervical cancer (10 papers, 2012 to 2025). A primary or metastatic malignant neoplasm involving the cervix. "In our study, inhibition of ECM stiffness using BAPN significantly impeded the ability of metastasis in cervical cancer, and these results are consistent with several studies confirming the effectiveness of chemical LOX inhibitors in vivo." (PMID 36684109, 2023). "The aim of this study was to investigate the effect of human umbilical vein endothelial cells on epithelial-to-mesenchymal transition of the cervical cancer cell line SiHa by studying the Notch1/lysyl oxidase (LOX)/SNAIL1 pathway." (PMID 31205475, 2019). "HIF-1 induction of LOX and LOXL-2 has been shown to promote migration in primary renal epithelial, and in breast and cervical cancer cells, which was associated with decreased E-cadherin expression." (PMID 23259746, 2012). "In cervical cancer study, β-aminopropionitrile (βAPN) inhibit LOX expression will blocked the EMT phenomenon of cervical cancer cells and inhibited invasion and migration under hypoxia in vitro; these data provide insights into the therapy and prevention of cervical cancer metastasis." (PMID 28036074, 2016). "Moreover, it has been shown that the LOX inhibitor, β-aminopropionitrile (β-APN), decreases the hypoxia-induced invasion and migration of cervical cancer cells." (PMID 28036074, 2016).
myocardial infarction (10 papers, 2018 to 2024). Gross necrosis of the myocardium, as a result of interruption of the blood supply to the area, as in coronary thrombosis. "In this study, higher levels of LOX were detected in more stable plaques and, interestingly, high levels of LOX mRNA in carotid plaques were associated with a lower incidence of myocardial infarction during the follow-up." (PMID 31615160, 2019). "A high LOX index reflects an increased risk for stroke and myocardial infarction." (PMID 28761986, 2018). "In human plaques, LOX presence was associated with a more stable plaque phenotype and LOX expression correlated negatively with markers of immune activation and the incidence of myocardial infarction (MI), suggesting a protective mechanism." (PMID 38329498, 2024). "The main aim of this work was to assess the consequence of LOX over-expression on acute ischemia-reperfusion injury and its impact on cardiac remodeling 28 days post-myocardial infarction." (PMID 35052579, 2021). "Accordingly, it has been reported that myocardial infarction induced by permanent LAD ligation in mice up-regulates fibroblast LOX expression reaching a peak that coincides with the minimal proliferative activity of these cells." (PMID 35052579, 2021). "Considering these data, it was plausible that LOX transgenesis would result in altered cardiac remodeling after myocardial infarction." (PMID 35052579, 2021). "Despite these findings, the impact of LOX on remodeling after myocardial infarction and the contribution of LOX-derived ROS to this process has not been previously investigated." (PMID 35052579, 2021). "As such, the LOX index was suggested to be a useful marker for the early diagnosis of stroke and myocardial infarction." (PMID 28761986, 2018). "Indeed, we and others have evidenced the up-regulation of LOX in mouse models of myocardial infarct, in both rats and mice." (PMID 35052579, 2021). "The importance of collagen quality in heart performance and the impact of LOX/LOXLs on cardiac fibroblast function highlight the interest of LOX/LOXLs-inhibitory therapies to slow HF progression and limit the detrimental impact of cardiac remodeling in response to myocardial infarction." (PMID 31615160, 2019). "The LOX index is a biomarker used to predict the onset of myocardial infarction and stroke." (PMID 28761986, 2018). "However, whether LOX influences acute myocardial infarction and post-infarct left ventricular remodeling and the contribution of LOX to myocardial oxidative stress following ischemia-reperfusion have not been analyzed." (PMID 35052579, 2021). "This, however, does not mean that LOX does not contribute to scar formation after myocardial infarction." (PMID 35052579, 2021). "Here, we show that cardiac LOX over-expression increased ROS generation, but it did not significantly alter acute ischemia-reperfusion injury, cardiac function or left ventricular remodeling after myocardial infarction." (PMID 35052579, 2021). "Our current results, from young animals with normal cardiac function, do not exclude that LOX transgenesis may differently affect post-myocardial infarction scar formation in aged animals." (PMID 35052579, 2021).
thyroid cancer (10 papers, 2016 to 2025). "In turn, thyroid cancer cells, through LOX expression, cross link fibroblast-derived collagen fibrils to generate mature and cross-linked collagen fibers." (PMID 36077709, 2022). "LOX, as well as Col-1, have been identified as markers for human thyroid cancer aggressiveness and predict poor overall survival in thyroid cancer patients." (PMID 36077709, 2022). "In thyroid cancer, dysfunction of COLL1 and LOX genes, promoted by BRAF and PTEN knockdown, were associated with ripping stiffen of Col1 matrix, enhancing cell motility and tumor progression." (PMID 28402931, 2017). "In thyroid cancer, LOX has been identified as the direct target of miR-30a, and downregulation of miR-30a mediates the upregulation of LOX and progression of thyroid cancer." (PMID 28036074, 2016). "For example, miR-30a antagonists inhibit LOX expression and affect thyroid cancer differentiation." (PMID 39247831, 2024). "Our analysis concludes that TIMP1, LOX, CD276, IFNA1, TLR2, and POSTN are identified as thyroid cancer biomarkers, which lead to the different clinical courses of a woman older than 55 years old with papillary thyroid cancer." (PMID 36120433, 2022). "Compared to TIMP1 and LOX, the relation between TLR2 and thyroid carcinoma was unclear, especially in PTC." (PMID 36120433, 2022). "In addition, LOX upregulation is also associated with anaplastic thyroid cancer progression and aggressive tall cell variant of PTC (TC-PTC) compared with the differentiated thyroid cancers [classic PTC (cPTC) and follicular variant of PTC (FV-PTC)] that may respond to BRAF activation." (PMID 36120433, 2022). "Unsupervised clustering confirmed the target genes (LOX, p16, α-SMA, COL1A1, and FAP) upregulation in thyroid cancers and in particular in those with BRAF-like signaling (115 out of 206 BRAF-like tumors clustered in the 5-genes overexpressing group; p-value < 0.0001)." (PMID 31906302, 2020). "Above all, in our results, TIMP1, LOX, and POSTEN had different expressions no matter what type of thyroid cancer and papillary thyroid cancer; even in pure classic PTC, high expression of those genes also predicted a poor prognosis." (PMID 36120433, 2022).
Aortic dissection (9 papers, 2016 to 2025). Aortic dissection refers to a tear in the intimal layer of the aorta causing a separation between the intima and the medial layers of the aorta. "Previous reports indicated that mutations in lysyl oxidase are associated with aortic dissection." (PMID 34769168, 2021). "It was demonstrated that dysregulation of interaction between LOX(high) fibroblast and smooth muscle cells contributed to the pathogenesis of aortic dissection." (PMID 39720896, 2024). "WES identified recurrent gain-of-function mutations in PRKG1 as causative for thoracic aortic aneurysms and acute aortic dissections, meanwhile MAT2A, LOX, and FOXE3 have been suggested as predisposing genes." (PMID 35892496, 2022). "The remaining 30 (17%) women were categorized in the ‘other’ group, which included women who harboured a rare PV in PKRG1 (n = 1), LOX (n = 1), or MYLK/FLNA (n = 1), or who had pre-existing aortic pathologies such as thoracic aortic dilatation (n = 23) or aortic dissection (n = 4)." (PMID 40576452, 2025).